HIF1A (hypoxia inducible factor 1 subunit alpha)
Diseases named in the same sentence as HIF1A in open-access papers (continued):
Sharing a sentence is not in itself a finding about the gene and the disease.
tumor (continued). "HIF-1α activation not only promotes metabolic reprogramming in tumor cells (e.g., enhancing glycolysis) but also induces vascular endothelial growth factor (VEGF) expression, leading to new blood vessel formation that supplies additional oxygen and nutrients to tumor cells." (PMID 41190142, 2025). "Upregulation of epithelial–mesenchymal transition (EMT)-related pathways, such as regulation of EMT by growth factors, HIF1α, TGFβ, and wound healing signaling pathways, further suggests a role for immune cells in supporting tumor cell plasticity, invasiveness, and metastasis." (PMID 41514627, 2025). "Additionally, HIF-1α can also promote tumor proliferation and invasion by modulating the expression of the proto-oncogene c-myc and the matrix metalloproteinase MMP9." (PMID 41154694, 2025). "Notably, HIF-1α-mediated regulation of the solid tumor’s microenvironment effectively modulates tumor sensitivity to anticancer therapies and thereby can contribute to disease progression." (PMID 41514626, 2025). "First, while VEGF is a powerful angiogenic signaling molecule, it is not the only signal for angiogenesis, and it is thought that the tumor cells can upregulate other angiogenic signaling pathways, such as hypoxia-inducible factor-1 alpha (HIF-1α) in the presence of bevacizumab." (PMID 40843765, 2025). "These gene signatures may provide insights into the activity of HIF-1α and hypoxia-related pathways, but tumor-specific panels are needed to account for variability across cancer types." (PMID 39981236, 2025). "Stabilized HIF-1α promotes angiogenic gene transcription and tumor adaptation." (PMID 40791817, 2025). "Furthermore, increased FAO not only supplies energy for rapid proliferation but also stabilizes HIF‐1α via metabolites such as acetyl‐CoA, reinforcing hypoxic signaling feedback and establishing a pro‐tumor metabolic‐signaling loop." (PMID 40904700, 2025). "Paradoxically, other investigations demonstrate that HIF-1α deficiency impairs NK cell cytotoxicity by reducing infiltration of cells expressing soluble VEGFR-1, an anti-angiogenic factor critical for suppressing tumor-associated neovascularization." (PMID 40791591, 2025). "CDK4/6i drives tumor cells to secrete MIF by activating the HIF-1α pathway." (PMID 41082324, 2025). "HIF-1α, a key regulator of the hypoxic response, induces the expression of genes involved in glucose uptake and glycolysis, promoting a shift toward anaerobic metabolism that supports tumor growth in oxygen-deprived regions." (PMID 40710528, 2025). "Epas1 might also promote infiltration of tumor-specific T cells into tumors, like Hif1a, since Epas1 controls expression of genes involved in tumor infiltration of immune cells, such as Plk4 and Tstd2." (PMID 39925817, 2025). "From the molecular mechanism perspective, the expression of AHNAK2 in the tumor hypoxic microenvironment is regulated by HIF-1α, which may drive tumor progression by inducing EMT and enhancing tumor stem cell characteristics." (PMID 41019085, 2025). "Consequently, we evaluated HIF-1α‘s contribution to ERCC6L-regulated tumor growth by genetically knocking down HIF-1α in A549 xenografts." (PMID 40691138, 2025). "ID stabilizes HIF-1α, which transcriptionally activates PD-L1 in tumor cells." (PMID 41190142, 2025). "Moreover, its impact on HIF-1α demonstrated HT’s potential to disrupt the hypoxic tumor microenvironment." (PMID 40002421, 2025). "Among the SRSF1-downregulated DEGs, those linked to tumor-related functions were primarily involved in glycolytic metabolism, the HIF1a signaling pathway, and metabolic pathways, rather than the upregulated genes." (PMID 39837814, 2025).
tumor (continued). "Hypoxic stress not only limits the effectiveness of therapies but also promotes tumor progression through the activation of hypoxia-inducible factor 1-alpha (HIF-1α), a transcription factor that induces angiogenesis by upregulating vascular endothelial growth factor (VEGF) expression." (PMID 41009654, 2025). "Compared to tumor cells treated with L-2-HG alone, HIF1A knockdown increased ferroptotic activity." (PMID 41198650, 2025). "Digoxin has been shown to inhibit HIF-1α transactivation, thereby suppressing tumor growth." (PMID 41228229, 2025). "Recently, Yang and Li (2023) reported that tricin has been shown to inhibit VEGFR-2 signaling by reducing ROS production in endothelial cells and decreasing VEGF expression by suppressing hypoxia-inducible factor-1α (HIF-1α) accumulation in tumor cells and damage.." (PMID 40341988, 2025). "AMPK acts as a key energy sensor that promotes mitochondrial biogenesis and oxidative metabolism under metabolic stress, while HIF-1α, often activated in the hypoxic tumor microenvironment, reprograms cellular metabolism toward glycolysis and contributes to resistance to chemotherapy." (PMID 40617805, 2025). "This insight may help further elucidate the molecular basis of HIF-1α-mediated tumor progression and may offer new therapeutic targets for hypoxia-related malignancies." (PMID 40760493, 2025). "In the future, patients with DEL phenotype and markedly elevated LDH levels may benefit from combination therapies that include HIF-1α inhibitors or targeted interventions against tumor metabolism." (PMID 41229502, 2025). "Tumors require abundant oxygen for cell proliferation, leading to hypoxic conditions in tumor tissues and often resulting in the overexpression of the hypoxia marker HIF-1α, which further stimulates tumor angiogenesis and participates in tumor cell energy metabolism and proliferation." (PMID 41444284, 2025). "HIF-1α acts as a transcription factor promoting tumor angiogenesis." (PMID 41019982, 2025). "It is known that metformin activates AMPK to downregulate glycolysis in tumor cells partially through inhibiting mTORC1 and HIF-1α, and it may impair glycolysis in Teff cells in a similar manner, weakening their anti-tumor immune response." (PMID 39776799, 2025). "Emerging mechanisms by which GDH1 promotes tumor progression have been elucidated in specific tumor types, including the upregulation of glucose transport, stabilization of HIF-1α,45 regulation of redox homeostasis, induction of EMT and anoikis, and mediation of ammonia recycling." (PMID 40487432, 2025). "A positive and significant correlation was observed between PD-L1% and HIF-1α% expression in tumor cells, irrespective of KRAS mutation status (Spearman r = 0.321; p = 0.003)." (PMID 39996842, 2025). "Separately, a mechanistic study using the Cancer Genome Atlas (TCGA) data and breast cancer models demonstrated that PDGFRβ, along with caveolin-1 (Cav-1), promotes autophagy in CAFs through the mTOR/FIP200/ATG13 pathway and enhances tumor invasiveness via HIF-1α/MCT4/MCT1 signaling." (PMID 41441395, 2025). "Resulting from inadequate tumour perfusion and rapid cellular proliferation, hypoxic conditions activate hypoxia-inducible factors (HIFs), particularly HIF-1α, which coordinates the transcription of genes involved in angiogenesis, metabolic reprogramming, invasion, and immune modulation." (PMID 40806577, 2025). "Since high expression of HIF-1α was correlated with tumor differentiation and stage in NSCLC, HIF-1α might be a better molecular target for improving NSCLC treatment access." (PMID 40011266, 2025). "However, recent perspectives suggest that the regulation of HIF-1α in tumors is more complex than merely promoting tumor development." (PMID 40948749, 2025).
tumor (continued). "Available data show that HIF-1α activation may also inhibit the effects of toxic reactive oxygen species (ROS) on tumor cells and may modulate glycolysis and pyruvate metabolism, as well as cancer cell metastatic potential and resistance to oncotherapy." (PMID 40227577, 2025). "After entering tumor cells, the siRNAs could inhibit HIF-1α expression and block the downstream fatty acid transporters fatty acid binding protein (FABP) 3 and FABP7 to deplete the lipid droplet pool in tumor cells." (PMID 41041050, 2025). "Tumor growth relies on angiogenesis, and ID regulates this process through the HIF-1α pathway." (PMID 41190142, 2025). "A high positive correlation was obtained between HIF-1α level and tumor size." (PMID 40429943, 2025). "Therefore, utilizing such a combined model can enhance the prediction of HIF-1α, which holds potential implications for estimating tumor sensitivity to radiotherapy or targeted therapies, as hypoxia is often associated with treatment resistance." (PMID 41189947, 2025). "In these contexts, mtDNA mutations can stabilize HIF-1α via altered redox signaling without completely disrupting respiration, thereby enhancing angiogenesis in hypoxic tumor microenvironments." (PMID 40869281, 2025). "By inhibiting mTOR, rapamycin reduces HIF-1α mRNA translation and suppresses tumor growth." (PMID 39757165, 2025). "Similarly, Lactobacillus paracasei-derived EVs (LpEVs) curb colorectal cancer cell proliferation by suppressing HIF-1α-mediated glycolysis, thereby disrupting the energy metabolism essential for tumor growth." (PMID 40429976, 2025). "Similarly, knockdown of HIF-1 significantly impairs UVM tumor progression, and silencing HIF-1α reduces UVM cell migration, invasion, and adhesion." (PMID 40823088, 2025). "Similarly to how HIF-1α upregulates glycolytic enzymes, its increased expression in tumor cells also induces glutaminolysis by directly or indirectly activating glutamine transporters." (PMID 41450919, 2025). "Furthermore, lactate stabilizes hypoxia-inducible factor 1-alpha (HIF-1α), a master regulator of glycolysis, which in turn upregulates PD-L1 expression on tumor cells, creating a vicious cycle of immune evasion." (PMID 40552288, 2025). "In addition, HIF-1a stimulates angiogenesis, producing abnormal blood vessels, favoring the targeted delivery of drugs to the tumor environment." (PMID 40149887, 2025). "HIF1A modulates hypoxia response and metabolism, aiding tumor adaptation under low oxygen." (PMID 40906153, 2025). "Owing to the PDT and HIF-1α inhibiting effect, TPPa-Y NPs exhibited a high in vivo tumor growth inhibition rate (96.3%), and could greatly inhibit the expression of HIF-1α within a solid tumor." (PMID 40395379, 2025). "Furthermore, the hypoxic tumour microenvironment induces EMT via the activation of factors such as HIF‐1α, thereby enhancing tumour invasiveness and metastatic potential." (PMID 40847555, 2025). "Similarly, in animal models, activation of HIF2α or replacement of HIF1α with HIF2α promotes aggressive tumor growth and invasion, whereas overexpression of stable HIF1α inhibits tumor growth." (PMID 40322886, 2025). "Others have also observed a reduction in this expression among insulinomas, suggesting a different factor that could also promote HIF-1α expression or angiogenesis in this tumor type." (PMID 40565098, 2025). "In conjunction with the previously enriched pathways from metabolomics, we speculate that HIF1A-mediated tumor metastasis may be closely related to its regulation of tumor cell iron death." (PMID 41198650, 2025). "Additionally, HBOT inhibits the activity of HIF-1α, blocking its mediated glycolysis and vascularization pathways, and reducing the metabolic adaptability of tumor cells." (PMID 40552269, 2025).
tumor (continued). "Recent research has shown that HIF-1α can directly associate with the HRE-4 within the PD-L1 promoter region, leading to a rapid and substantial upregulation of PD-L1 expression on the surface of tumor cells under hypoxic conditions." (PMID 41311849, 2025). "Importantly, downregulating UQCRB also impairs cancer stem cell-like traits in glioblastoma by reducing c-Met signaling, HIF-1α activation, and mitochondrial membrane potential, highlighting its potential in combating tumor recurrence and angiogenic niches." (PMID 40869281, 2025). "On the other hand, YC-1 may effectively inhibit the overexpressed HIF-1α and alleviate tumor hypoxia, which can further enhance the PDT efficacy of TPPa." (PMID 40395379, 2025). "Tumor cells exploit HIF-1α signaling to adapt to hypoxia through multiple strategies." (PMID 40171017, 2025). "mTOR activation leads to more vascularised tumours by activating HIF-1α-induced VEGF signalling." (PMID 40806771, 2025). "Previous research has established that heat shock 70-kDa protein 1-like (HSPA1L) is crucial in promoting CRC proliferation via HIF-1α activation and cellular prion protein (PrPC) regulation within tumor niches, and its expression has already been linked to CRC prognosis." (PMID 39886381, 2025). "Overexpression of GLUT1 is driven by hypoxia-inducible factor-1α (HIF-1α), c-Myc, and other pathways which have been correlated with tumor aggressiveness as well as poor prognosis Recent studies have highlighted the therapeutic potential of targeting GLUT1 in GBM." (PMID 40563757, 2025). "HIF1A (Hypoxia-Inducible Factor 1-Alpha) is a core transcription factor for cells to sense and respond to a hypoxic environment, playing a key role in pathophysiological processes such as tumor progression, inflammation, and metabolic reprogramming." (PMID 41190029, 2025). "However, studies demonstrated that this drug increases the level of ROS in tumor cells, which stabilizes hypoxia-inducible-factor-1α (HIF-1α), a factor leading to tumor tolerance to chemotherapy." (PMID 40006612, 2025). "Emerging strategies to overcome hypoxia-mediated resistance focus on tumor vasculature normalization using anti-angiogenic agents (e.g., axitinib), HIF-1α signaling inhibition via digoxin analogs, and lactate export modulation through monocarboxylate transporter (MCT) blockade." (PMID 41209702, 2025). "This preference is partly due to the overexpression of HIF-1α in tumor cells." (PMID 39061859, 2024). "Importantly analysing the TCGA database, in HNSCC tumour tissue there is a significantly increased expression of HIF‐1α transcripts compared to normal tissue." (PMID 38899556, 2024). "CircRNF20 is found to accelerate tumor progression by targeting miR-487a/HIF-1α/HK2 in BC." (PMID 38799423, 2024). "Similarly, the HIF‐1A inhibitor (PX‐478)‐treated A549 tumor spheroids remarkably altered the mir‐210‐3p and CCL2 gene expressions in hypoxic conditions." (PMID 35658112, 2024). "HIF-1α is responsible for the transcription of genes that allow adaptation to hypoxic environments, promoting tumor cell progression by maintaining growth, facilitating vascular mimicry and conferring properties such as invasion, migration, and drug resistance." (PMID 38339408, 2024). "The biology seen in miR-18a/low tumours may be attributed to such a buffering function where low levels fail to buffer the mean levels of miR-18a target genes such as HIF1A and thus lead to alternate phenotypic changes." (PMID 38786043, 2024). "HIF1, a heterodimer of HIF1α and HIF1β, is an important mediator of the hypoxic response of tumor cells and controls the up-regulation of a number of factors important for solid tumor expansion including the angiogenic factor vascular endothelial-derived growth factor (VEGF)." (PMID 38802766, 2024). "Jie Du San Gen Decoction could reverse 5-FU resistance by suppressing glycolysis through the PI3K/AKT/HIF-1α signaling pathway, inducing apoptosis and enhancing anti-tumor activity." (PMID 39354520, 2024).
tumor (continued). "In addition, the tumor suppressor LKB1 was reported to inhibit the growth of tumor cells by regulating HIF-1α." (PMID 38172980, 2024). "Since hypoxia and ROS are the main drivers in immune exhaustion, ROS-responsive manganese dioxide (MnO2) NPs are developed to carry the HIF-1α inhibitor (acriflavine) to the tumor sites, successfully relieving T-cell exhaustion and activating tumor-specific immune responses." (PMID 38338674, 2024). "One possible explanation is that high HIF-1α expression correlates with increased tumor malignancy." (PMID 39723370, 2024). "Moreover, a hypoxic marker, HIF1α, is markedly elevated in the tumor areas of KPC mice, suggesting these PDAC tumors with desmoplasia is highly hypoxic." (PMID 38687749, 2024). "In our previous studies, we found that propranolol could reverse norepinephrine-induced tumor cell EMT through the modulation of β-AR/TGF-β1/HIF-1α/Snail and β-AR/TGF-β1/p-Smad3/Snail pathways." (PMID 38294713, 2024). "Additionally, the inhibition of the angiogenic factors VEGF and HIF-1α further supports the role of solanine in suppressing angiogenesis, which is critical for tumor progression." (PMID 39124760, 2024). "Moreover, even at extremely low doses, IR‐LND@Lip was able to significantly inhibit the OCR of tumor cells and efficiently downregulate the expression of PD‐L1 and HIF‐1α protein in tumor cells." (PMID 38704675, 2024). "HGSC patients exhibiting an immunoreactive profile trigger an immune response, which results in the recruitment of pro-angiogenic monocytes from the bone marrow, increased intratumoral hypoxia, upregulated HIF-1α, and a high pericyte coverage of the tumor vascular system." (PMID 38727322, 2024). "Because HIF1α deficiency reduces CXCL1-mediated macrophage recruitment, hypoxia in TECs affects TAM behavior and recruitment, thus altering the interaction between TAMs and TECs in the tumor microenvironment." (PMID 38824197, 2024). "HIF-1α promotes the generation of ATP in numerous tumor cell types." (PMID 38612754, 2024). "GC Patients highly expressing HIF1A protein might be prone to tumor progression, poorly differentiated GC cell types, and a high VEGF expression." (PMID 38877062, 2024). "Intratumoral hypoxia could induce hypoxia‐inducible factor 1α (HIF‐1α) overexpressed in tumours, and there is a close relationship between tumour treatment failure and increased mortality." (PMID 38013642, 2024). "In hypoxic tumor microenvironments, HIF-1α can induce the activation of LDHA." (PMID 38841361, 2024). "In addition, tumor cells undergoing metabolic reprogramming use transcription factors such as HIF-1α and c-Myc to up-regulate glycolytic enzyme activity, thereby increasing glycolytic efficiency." (PMID 39539540, 2024). "Furthermore, pretreatment of baicalein increased the sensitivity of tumor cells to 6Gy ray by down-regulating HIF-1A and PKM2, the key regulators of glycolysis." (PMID 39654621, 2024). "We found that curcumin suppressed tumor progression via the TLR4/HIF-1α/PD-L1 pathway, suggesting that curcumin may be a potent immunomodulator for treating CRC." (PMID 38612546, 2024). "Therefore, tumor hypoxia is considered a potential therapeutic target, and many studies have reported that inhibition of HIF-1α can suppress tumor growth by reducing its activity." (PMID 38562672, 2024). "Importantly, further KO of Bnip3 and Hif1α/2α abrogated tumor growth delay observed in Vhl-KO MC38 tumors." (PMID 39050705, 2024). "Our experiments showed that NCL-1 treatment also reduced HIF1A in the central regions of the xenograft tumors, where blood vessels were also lost and tumor cell proliferation was suppressed in addition to apoptosis or differentiation to ganglion cells being induced." (PMID 39458030, 2024). "Additionally, in vivo studies have revealed that oleuropein inhibits the high-fat diet-induced accumulation of adipocytes and M2-MΦs, as well as the expression of VEGF-A, -D, and HIF-1α in tumor tissues." (PMID 39203892, 2024).